STMN4 (stathmin 4)
Description:
Exhibits microtubule-destabilizing activity.
Synonyms: RB3
Tractability: Small molecule: a structure with a bound ligand is known. PROTAC: ubiquitination databases record sites on it; its protein half-life has been measured.
Gene: Protein-coding gene on chromosome 8 (27,235,308 to 27,258,435, reverse strand). Ensembl gene ENSG00000015592.
Subcellular location: Golgi apparatus; Cell projection, growth cone; Cell projection, axon
Subcellular location (Human Protein Atlas): Golgi apparatus; Vesicles
Gene Ontology:
Molecular function: tubulin binding
Biological process: microtubule depolymerization; neuron projection development; regulation of microtubule polymerization or depolymerization
Cellular component: cytoplasm; neuron projection; axon; Golgi apparatus; growth cone
Genetic constraint (gnomAD): Loss-of-function variants: 12 observed, 30.56 expected, observed/expected ratio (o/e) 0.39, 90% interval 0.25 to 0.64. The upper end of that interval is the gene's LOEUF score, 0.64, which puts it in group 2 of 6, group 1 being the genes least tolerant of losing a copy. Missense variants: 181 observed, 278.16 expected, observed/expected ratio (o/e) 0.65, 90% interval 0.58 to 0.74. Synonymous variants: 114 observed, 113.01 expected, observed/expected ratio (o/e) 1.01, 90% interval 0.87 to 1.18.
Homologues: Orthologues: dog STMN4 (99% identical), pig STMN4 (99% identical), guinea pig STMN4 (99% identical), rat Stmn4 (98% identical), rabbit STMN4 (91% identical), mouse Stmn4 (87% identical), chimpanzee STMN4 (81% identical), macaque STMN4 (81% identical), tropical clawed frog stmn4 (75% identical), zebrafish stmn4l (66% identical), Drosophila melanogaster stai (34% identical). Paralogues in human: STMN2 (54% identical), STMN3 (51% identical), STMN1 (44% identical), STMND1 (22% identical).
Diseases named in the same sentence as STMN4 in open-access papers:
STMN4 is named in the same sentence as 14 diseases in open-access papers, as found by Europe PMC text mining. Sharing a sentence is not in itself a finding about the gene and the disease. The quoted sentences say what the papers report.
neuroblastoma (3 papers, 2016 to 2026). Neuroblastoma (NB) is the most common solid, extracranial childhood tumor. "Conversely, a transcriptomic study on neuroblastoma SK-N-SH cells revealed that SARS-CoV-2 infection induced a downregulation of several members of building blocks of the cytoskeleton, as well as some of their regulators (i.e., TUBA1A, TUBA4A, TUBB4A, STMN4, TMSB15A, SYNPO2)." (PMID 37896797, 2023).
schizophrenia (1 paper, 2021). A major psychotic disorder characterized by abnormalities in the perception or expression of reality. "For both α-HPy and α-CJe, several established schizophrenia candidate proteins with cross-reactivity to either of these antibodies could be identified including Syt5, Slc17a7, Stmn4, and Ncan." (PMID 32860155, 2021).
tumor (3 papers, 2012 to 2022). "Cox regression analysis demonstrated that tumor stage, STMN4 and FAM135B dysregulation were independent prognostic factors for COAD survival outcomes." (PMID 35610288, 2022).
STMN4 also shares sentences with these, for which no sentence is quoted: cancer (2 papers); leukaemia (2); autism (1); Cachexia (1); Cervical (1); hepatoma (1); intestinal polyp (1); oral cancer (1); osteosarcoma (1); periodontitis (1); skin papilloma (1).